DDX39BP2 (DEAD-box helicase 39B pseudogene 2)
Synonyms: BPG309N1.15; formerly BAT1P2
Gene: Transcribed unprocessed pseudogene on chromosome 6 (29,993,209 to 29,993,605, forward strand). Ensembl gene ENSG00000238024.
Diseases named in the same sentence as DDX39BP2 in open-access papers:
DDX39BP2 is named in the same sentence as 1 disease in open-access papers, as found by Europe PMC text mining. Sharing a sentence is not in itself a finding about the gene and the disease.
DDX39BP2 shares sentences with these, for which no sentence is quoted: COVID-19 (1 paper).